DYRK2 (dual specificity tyrosine phosphorylation regulated kinase 2)
Diseases named in the same sentence as DYRK2 in open-access papers (continued):
Sharing a sentence is not in itself a finding about the gene and the disease.
glioma (9 papers, 2020 to 2024). A benign or malignant brain and spinal cord tumor that arises from glial cells (astrocytes, oligodendrocytes, ependymal cells). "Regarding nervous system disease, DYRK2 has been implicated in neuroblastoma, glioma, epilepsy, neuroinflammation, Alzheimer’s disease, Parkinson’s disease, spinal cord injury and virus infection." (PMID 36161154, 2022). "DYRK2 is also associated to gliomas, the most general primary nervous system tumor, which is characterized by a forceful malignant proliferation and invasion and high mortality." (PMID 36161154, 2022). "A reduction in DYRK2 has also been linked to the enhanced migration and invasion of breast, glioma and ovary cancer cell lines." (PMID 32751160, 2020). "In addition, DYRK2 has been reported to be implicated in the suppression of EMT in glioma since it is associated with decreased expression of Vimentin and SNAIL and stabilization of E-cadherin levels." (PMID 32462403, 2020). "DYRK2 is expressed in human tumors and can suppress glioma cell migration, affecting E-cadherin and vimentin expression in the PI3K/AKT/GSK3β signaling pathway." (PMID 38584840, 2024). "In gliomas, the expression of DYRK3 and CLK3 correlated with worse survival, while DYRK1A, DYRK2 and CLK1 were associated with better disease outcomes." (PMID 38398225, 2024). "A recent unbiased deep multiomics study looking at the proteome, phosphoproteome, and transcriptome of murine high-grade brain cancer glioma model reported 41 kinases including DYRK2 exhibiting higher activity and rewired substrate signaling." (PMID 33376136, 2021). "DYRK2 expression in glioma correlates with the expression of E-cadherin, and its ectopic expression in glioma cell lines inhibits migration through the PI3K/AKT signaling pathway." (PMID 33067577, 2020). "Besides, in human glioma cell lines, DYRK2 downregulation resulted in migration up-regulation and lower E-cadherin expression both associated with cancer progression and metastasis." (PMID 36161154, 2022). "These contradictory results suggest that the role of DYRK2 in gliomas might be cell-, tissue- or patient-specific." (PMID 36161154, 2022). "To summarize, a growing body of evidence suggests that DYRK2 is mainly involved in neuroblastoma, glioma, epilepsy, and neuroinflammation but also could be involved in traumatic and neurodegenerative diseases and Rabies virus infection." (PMID 36161154, 2022). "DYRK2 knockdown led to upregulation of mesenchymal markers with consequent downregulation of epithelial E-cadherin mRNA in colon cancer and promotion of proliferation and migration of glioma cells." (PMID 33376136, 2021). "Likewise, a weaker DYRK2 expression was associated with a worse prognosis in ovarian serous adenocarcinoma, CRC, HCC, glioma and non-Hodgkin’s lymphoma patients." (PMID 32751160, 2020). "Conversely, DYRK2 was downregulated in lung adenocarcinoma and squamous cell carcinoma, diffuse large B-cell lymphoma, CRC, hepatocellular carcinoma (HCC) and high-grade glioma." (PMID 32751160, 2020).
multiple myeloma (8 papers, 2020 to 2025). "DYRK2 Inhibitor thus has been developed for the treatment of prostate cancer, triple-negative breast cancer and multiple myeloma." (PMID 40190550, 2025). "To obtain a comprehensive list of potential DYRK2 targets, we treated the myeloma U266 cells with C17 and carried out quantitative phosphoproteomic analyses." (PMID 35439114, 2022). "In fact, mice bearing syngrafted/xenografted myeloma cells with genetic depletion of DYRK2 exhibit significantly slower myeloma disease progression and reduced bone degeneration." (PMID 33376136, 2021). "Interestingly, targeting one such proteasome-regulating kinase, DYRK2, in vivo dramatically reduced tumor burden in multiple myeloma and triple-negative breast cancer (TNBC) mouse models." (PMID 35088066, 2022). "We have recently identified LDN192960 as a selective DYRK2 inhibitor and showed that LDN192960 could alleviate multiple myeloma and triple-negative breast cancer progression by inhibiting DYRK2-mediated proteasome phosphorylation." (PMID 35439114, 2022). "DYRK2 is overexpressed in several tumors, including triple-negative breast cancer and multiple myeloma, which are known to rely heavily on proteasome activity for progression, and perturbation of DYRK2 activity impedes cancer cell proliferation and inhibits tumor growth." (PMID 35439114, 2022). "The fact that the DYRK2 inhibitor alleviates myeloma burden in vivo suggests DYRK2 could indeed be a viable in vivo target for myeloma therapeutics." (PMID 33376136, 2021). "Indeed, potent and selective small-molecule inhibitors of DYRK2 exhibit in vitro and in vivo anti-tumor activity in triple-negative breast cancer and myeloma models." (PMID 33376136, 2021). "Additionally, DYRK2 depleted and parental multiple myeloma cell lines such as MPC11 and 5TGM1 have been used in xenograft models, proving a negative relation with mice survival." (PMID 32462403, 2020). "Initially, we had thought that this pathway was specific primarily for TNBC and myeloma; however, this work shows that HSF1 and DYRK2 expressions correlate across cell states and therapy responses in diverse cancer types." (PMID 36622366, 2023). "TIR-199 can induce cell death in myeloma, TNBC, and non-small cell lung cancer, and can trigger synergistic cytotoxicity in combination with DYRK2 inhibitor LDN192960." (PMID 35088066, 2022). "In fact DYRK2 inhibitor LDN192960 significantly reduces proteasome activity and impedes systemic bone degeneration in immunocompetent mouse myeloma models and induces synergistic cytotoxicity in cancer cells in combination with proteasome inhibitors." (PMID 35088066, 2022). "The potent and selective DYRK2 inhibitor, LDN192960, induces cytotoxicity in myeloma cells both in vitro and in vivo with minimal off-target effects." (PMID 33376136, 2021). "In this context, two DYRK2 inhibitors, the natural drug curcumin and the small-molecule LDN192960, impaired cell proliferation and invasion and induced apoptosis in multiple myeloma and TNBC cell lines." (PMID 32751160, 2020). "Furthermore, DYRK2 was targeted by a small molecule LDN192960 for the treatment of for triple-negative breast cancer and multiple myeloma." (PMID 40190550, 2025). "DYRK2 inhibitors in combination with proteasome inhibitors synergistically induced cytotoxicity, while LDN192960 alone bypassed bortezomib resistance in myeloma cells and reduced matrigel invasion in TNBC cells." (PMID 36622366, 2023). "Proteasome-inhibitor resistance is extensively observed in multiple myeloma patients and hence dual targeting of HSF1 and DYRK2 could be an alternative strategy to combat the refractory disease." (PMID 36622366, 2023).
multiple myeloma (continued). "It has also been reported that curcumin, an active ingredient in Curcuma longa, may be a DYRK2 inhibitor and decreases 26S proteasome activity through DYRK2 inhibition in TNBC and multiple myeloma cell lines, thereby inhibiting tumor proliferation." (PMID 37886981, 2023). "We had previously established DYRK2 as a direct HSF1 phosphorylating kinase and showed that DYRK2 inhibition leads to impediment of the cell cycle via accumulation of proapoptotic factors leading to tumour regression of multiple myeloma and TNBC in vivo." (PMID 36622366, 2023). "DYRK2 phosphorylates and activates both HSF1 and the 26S proteasome and thereby activates the proteotoxic stress pathway promoting tumorigenesis in cancers such as triple-negative breast cancer (TNBC) and multiple myeloma (MM)." (PMID 33376136, 2021). "Moreover, the upregulation of DYRK2 was described in triple-negative breast cancer (TNBC) and multiple myeloma." (PMID 32751160, 2020). "Moreover, the same group later described how the inhibition of DYRK2 activity mediated by curcumin and LDN192960 reduces cell proliferation and induces cell death, thus compromising triple-negative breast cancer (TNBC) and multiple myeloma (MM) growth." (PMID 32462403, 2020).
lung cancer (7 papers, 2015 to 2023). A malignant neoplasm involving the lung. "We observed a significant increase in DYRK2 expression in healthy lung specimens compared to corresponding lung cancer samples, suggesting that SIAH2 overexpression is associated with decreased expression of its substrates." (PMID 26580787, 2015). "In particular, mutual regulation has been described for SIAH2 and DYRK2; indeed, an increase in the SIAH2 protein has been observed in lung cancer tissue and linked to DYRK2 downregulation." (PMID 32751160, 2020). "A similar discrepancy between the DYRK2 protein and mRNA was also detected in liver and lung cancers between a published protein data analysis and our TCGA analysis of mRNA changes." (PMID 32751160, 2020). "We then analyzed the possible impact of the previously demonstrated mutual regulation between SIAH2 and DYRK2 in human lung cancer by immunohistochemistry." (PMID 26580787, 2015). "Our findings indicate an important association between the expression of SIAH2 and lung cancer, which is also associated with the histological tumor grade, 18FDG uptake and with a decrease in the expression of SIAH2 substrates such as DYRK2." (PMID 26580787, 2015). "DYRK2 expression significantly decreased in tissue samples from patients with lung cancer." (PMID 37886981, 2023). "The expression level of DYRK2 was significantly increased in lung cancer tissues compared with normal tissues, which might indicate a potential role of DYRK2 in lung cancer development and/or progression." (PMID 35993327, 2022). "Multiple publications carrying out sequencing or immunohistochemistry to study mRNA/protein levels of DYRK2 have suggested that DYRK2 is a tumor suppressor in colorectal, liver, brain, and lung cancers and that the kinase promotes chemosensitivity in ovarian cancer." (PMID 33376136, 2021). "The controversial role of DYRK2 is best highlighted in breast and lung cancers." (PMID 33376136, 2021). "Over the last decade, the CMGC kinase DYRK2 has been reported as a tumor suppressor across various cancers triggering major antitumor and proapoptotic signals in breast, colon, liver, ovary, brain, and lung cancers, with lower DYRK2 expression correlated with poorer prognosis in patients." (PMID 33376136, 2021). "However, two independent studies report that higher protein or mRNA expression of DYRK2 is a favorable marker in pulmonary adenocarcinoma and non–small-cell lung cancer (NSCLC)." (PMID 33376136, 2021). "Notably, the role of DYRK2 in lung cancer has been investigated only in patient tissue samples." (PMID 37886981, 2023). "Moreover, DYRK2 was also overexpressed among lung cancer (LUAD and LUSC) in TCGA data." (PMID 35993327, 2022). "Hence, using a similar strategy as suggested previously to generate conditional DYRK2 depletion in genetically engineered lung cancer mouse models for NSCLC, squamous-cell lung cancer, and other subtypes could provide more clarity to this debate." (PMID 33376136, 2021). "With a relatively loose threshold (p < .2), the genes Dhx16, Upf2, Denr, Notch3, Dyrk2, Sec61a1, Hmmr, and Noa1 were reversed in at least three treatment protocols and most of these genes were reported to be related to COPD or lung cancer." (PMID 35993327, 2022). "SIAH2 protein and mRNA levels were found to be higher in samples of patients with lung cancer and exhibited a negative correlation with DYRK2 expression." (PMID 33376136, 2021).
ovarian carcinoma (7 papers, 2020 to 2024). A malignant neoplasm originating from the surface ovarian epithelium. "The role of DYRK2 as an oncogene in ovarian cancer was investigated using patient tissue samples and cell lines." (PMID 37886981, 2023). "The role of DYRK2 in ovarian cancer has been investigated in tissue samples, cell lines, and xenograft mouse models." (PMID 37886981, 2023). "In breast and ovarian cancer in particular, DYRK2 increases migratory activity of tumor cells through activation of c-JUN, c-Myc, and Snail signaling." (PMID 33804169, 2021). "DYRK2 phosphorylates amino acids and plays a key role in breast and ovarian cancer development." (PMID 36202838, 2022). "Besides the alterations to the cellular levels of DYRK2, changes in the substrate selectivity have been seen in relation to Snail in ovarian cancer, with DYRK2 phosphorylation prevented by the prior p38-mediated phosphorylation of Snail." (PMID 32751160, 2020). "In this regard, DYRK2 phosphorylates the EMT transcription factor Snail, priming it for ubiquitination-mediated degradation, which provides additional evidence that DYRK2 prevents the activation of aggressive phenotypes in breast and ovarian cancer cells." (PMID 32751160, 2020). "Cancer mutations could result in incomplete EDVP complex formation, and incomplete EDVP can exhibit oncogenic prosurvival role because DYRK2+EDD alone degrades the proapoptotic factor modulator of apoptosis protein 1 independently of DDB1 and VPRBP in ovarian cancer." (PMID 33376136, 2021).
triple-negative breast carcinoma (7 papers, 2020 to 2025). An invasive breast carcinoma which is negative for expression of estrogen receptor (ER), progesterone receptor (PR), and human epidermal growth factor receptor 2 (HER2). "In TNBC (triple negative breast cancer) cells, DYRK2 actively regulates the nuclear stability and activity of HSF1 by phosphorylation at ser320 and ser32618." (PMID 36104345, 2022). "For example, it has been reported that DYRK2 inhibition by LDN192960 affects the tumorigenic potential of triple-negative breast cancer cells due to DYRK2 activity on 26S proteasome." (PMID 32462403, 2020). "Additionally, it has been demonstrated that DYRK2 suppression by knockout or inhibition with curcumin or LDN192960 leads to an increase of apoptosis in triple-negative breast cancer cells and xenografts due to a reduction of the 26S proteasome activity." (PMID 32462403, 2020). "High nuclear levels of DYRK2 and heat shock factor 1 (HSF1) have been detected in triple-negative breast cancer (TNBC) tissues, and high nuclear DYRK2 levels significantly reduced cancer-specific survival in TNBC and triple- and AR-negative patient samples." (PMID 37886981, 2023). "Here we demonstrate that in triple-negative breast cancer (TNBC) cells, the dual specificity tyrosine-regulated kinase 2 (DYRK2) phosphorylates HSF1, promoting its nuclear stability and transcriptional activity." (PMID 33268814, 2021).
chronic myeloid leukemia (5 papers, 2020 to 2023). "DYRK2 levels are low in chronic myeloid leukemia (CML) cell lines (K562, KU-812, and KBM5), whereas DYRK2 expression is high in hematopoietic stem cells (lineage-negative Sca-1+ c-Kit+ (LSK) cells) from Krüppel-like factor 4 (KLF4) knockout mice." (PMID 37886981, 2023). "Besides solid tumors, chronic myeloid leukemia (CML) cell lines exhibit significantly lower protein levels of DYRK2 than other hematological cancer cell lines." (PMID 33376136, 2021). "In this review, we briefly discuss molecular maintenance in leukemia stem cells in chronic myeloid leukemia and provide a more in-depth discussion of the dual-specificity kinase DYRK2, which has been identified as a novel actionable checkpoint in a critical leukemic network." (PMID 33067577, 2020). "Likewise, further efforts have been done to elucidate DYRK2 role in chronic myeloid leukemia (CML) stem/progenitor cells." (PMID 32462403, 2020).
leukemia (5 papers, 2020 to 2023). A malignant (clonal) hematologic disorder, involving hematopoietic stem cells and characterized by the presence of primitive or atypical myeloid or lymphoid cells in the bone marrow and the blood. "This tumor-suppressor role of DYRK2 seems to be CML specific because all other leukemia subtypes tested exhibited naturally elevated protein levels of DYRK2 at basal conditions, suggesting alternate driving mechanisms for tumorigenesis." (PMID 33376136, 2021). "Notably, the role of DYRK2 in leukemia has been investigated in cell lines and primary cultures, while its role in lymphoma has been studied only in patient samples." (PMID 37886981, 2023). "Although this study was carried out using 239T cells, this finding is particularly relevant to leukemia because a hypoxic bone marrow environment may contribute to DYRK2 upregulation by SIAH2 inhibition." (PMID 33067577, 2020).
lung adenocarcinoma (5 papers, 2016 to 2026). A carcinoma that arises from the lung and is characterized by the presence of malignant glandular epithelial cells. "A pan-cancer analysis revealed a trend toward a negative correlation between USP28 levels and the active form of DYRK2 across different tumor types, with high statistical significance primarily driven by lung adenocarcinoma (LUAD)." (PMID 40858801, 2026). "This is reiterated in the TCGA lung adenocarcinoma and esophageal cancer cohort wherein tumor samples expressed higher DYRK2 mRNA than normal tissue." (PMID 33376136, 2021). "In contrast, amplification of DYRK2 gene occurs in esophageal/lung adenocarcinoma, implying the role of DYRK2 as a potential oncogene." (PMID 27532268, 2016). "And yet others have noted amplification and overexpression of DYRK2 in esophageal and lung adenocarcinoma, as well as gastric stromal tumor, suggesting that DYRK2 can behave as a potential oncogene, although the protein levels of the gene were not examined." (PMID 27532268, 2016). "The first paper on DYRK2 in cancer was published in 2003, and it was reported that DYRK2 mRNA amplification and overexpression were detected using oligonucleotide microarrays in lung adenocarcinomas." (PMID 37886981, 2023). "Mechanistically, in lung adenocarcinoma and squamous-cell lung cancer, E3 ubiquitin ligase SIAH2 targets DYRK2 for proteasomal degradation." (PMID 33376136, 2021).
pancreatic cancer (4 papers, 2019 to 2025). "We also detected DYRK2 and GIL2 protein in five pancreatic cancer cell lines." (PMID 33995647, 2021). "As we previously observed in different cell lines, a considerable number of tissues present in a high number of patients showed low levels of DYRK2 expression and a high NOTCH1 abundance, from which the differences observed in ovarian, cervical, colorectal or pancreatic cancer stand out." (PMID 31605148, 2020). "Analyses of HPDE cells and a panel of PDA cell lines indicated that YSK4 and DYRK2 are not expressed in pancreatic cancer cell lines." (PMID 31719634, 2019).